SLIT2 (slit guidance ligand 2)
Diseases named in the same sentence as SLIT2 in open-access papers (continued):
Sharing a sentence is not in itself a finding about the gene and the disease.
tumor (continued). "Nonetheless, SLIT2 has been shown to be silenced in several invasive tumors and in cancer cell lines, including PDAC cells, and conversely, high levels of SLIT2 mRNA are associated with suppressed tumor growth in vivo." (PMID 32807784, 2020). "However, the role of the genetic variants on the interaction of SLIT2/ROBO1/4, potentially altering the anti-angiogenic pathway and overall tumour suppressive function, is yet to be elucidated." (PMID 33318575, 2020). "Since both signaling pathways contribute to EMT activation, we suggested that SLIT2 might serve as a potential tumor metastasis indicator." (PMID 32795291, 2020). "One possible explanation for this observation inhibition of the WNT/β-catenin pathway by Slit2/Robo signaling, which enhances the formation of β-catenin and E-cadherin complexes, increases tumor cell adhesion and inhibits tumor invasion and migration, thereby improving patient prognosis." (PMID 32670371, 2020). "Finally, they selected three of these markers (the genes HS3ST2, SLIT2 and SEPTIN9) for combination with the FGFR3 mutations in a logistic regression model, obtaining a sensitivity of 94.5% (96% in high-grade tumours) and a specificity of 75.9%." (PMID 32664878, 2020). "Moreover, TGF-β1 expression was positively correlated with Slit2 upregulation in the tumor tissues of CRC." (PMID 31242633, 2019). "Specific blockage of Slit2 binding to Robo1 could inactivate TGF-β/Smads signaling, although whether TGF-β/Smads signaling is involved in Slit2/Robo1-induced tumor growth and metastasis of CRC is still to be demonstrated." (PMID 31242633, 2019). "In summary, our studies have elucidated that high levels of Slit2 in tumor tissues and serum may be a potential biomarker for CRC." (PMID 31242633, 2019). "This study aims to understand whether tumorigenesis changes the expression ratio of Slit2-WT and Slit2-ΔE15 in a tumor microenvironment." (PMID 30717252, 2019). "The blocking of Slit2/Robo1 signaling may suppress tumor metastasis by the partial inactivation of the TGF-β/Smads pathway." (PMID 31242633, 2019). "Furthermore, TECs are able to downregulate tumor suppressive factors such as Slit2, thereby promoting tumor progression." (PMID 31641356, 2019). "Herein, we speculate that the blocking of Slit2/Robo1 signaling inhibits tumor metastasis through the targeting of TGF-β1." (PMID 31242633, 2019). "Our findings provide a novel insight into the biology of OS progression and raise the possibility that targeting the SLIT2/ROBO1 axis could be a beneficial clinical anti-tumor strategy for OS patients." (PMID 29523788, 2018). "Additionally, SLIT2/ROBO1 signalling has been shown to inhibit tumour cell proliferation and migration." (PMID 29743814, 2018). "Of these, CAV1, SFRP2, TMEFF2, SST and SLIT2 have been identified as tumor-suppressor genes." (PMID 25997610, 2015). "It is reported that Slit2, as a potent lymphangiogenic factor, contributes to tumor lymphatic metastasis; VEGF-A treated lymphatic endothelial cell exhibited STAT3 activation in the nucleus, thereby enhancing lymphatic endothelial cell migration and increased tube formation." (PMID 26187792, 2015). "The Slit2/Robo1 signaling can induce precancerous lesions of the intestine and tumor progression." (PMID 25605242, 2015). "SLIT2 has been postulated for several years to act as a tumour suppressor gene in several cancers." (PMID 23671423, 2013). "SLIT2 suppresses tumor growth by coordinating regulation of the β-catenin and PI3K/AKT pathways." (PMID 23381221, 2013). "Our results indicated that SLIT2 was hypermethylated in both tumor tissues and tumor cell lines." (PMID 23381221, 2013). "The deletion frequency of SLIT2 increased gradually during tumor progression." (PMID 22719878, 2012). "Thus, upregulation of Robo1 in response to the decrease in miR-218 induced a reactive upregulation of the Slit-Robo1 pathway through its interaction with Slit2, thus facilitating tumor cell invasion and metastasis." (PMID 20300657, 2010).
tumor (continued). "Meanwhile, Robo1, one of several Slit receptors, is upregulated in response to the decrease in miR-218, which in turn induced a reactive upregulation of the Slit-Robo1 pathway through an interaction with Slit2, thus facilitating tumor cell migration and invasion." (PMID 20300657, 2010). "SLIT2 was present in most of the tumor tissues and HCC cell lines although at variable levels." (PMID 19114000, 2008). "Furthermore, re-expression of SLIT2 inhibited the growth of cancer cell lines so that SLIT2 appears to function as a novel tumour suppressor gene (TSG)." (PMID 15534609, 2004). "However, epigenetic inactivation of SLIT2 is less frequent than RASSF1A in the tumour types analysed." (PMID 14735202, 2004). "Interestingly, Slit2 also reduced the number of pro‐tumor M2‐like macrophages and MDSCs." (PMID 35838343, 2023). "The results demonstrated that ROBO1-FL-expressing tumour cells showed increased proliferation and colony formation ability in the presence of recombinant SLIT2 (rSLIT2), and this advantage could be abolished by sROBO, a soluble peptide containing the first 2 Ig domains as a ligand-binding trap." (PMID 36792623, 2023). "Besides this, the SLIT2/ROBO1 pathway seems to play contradictory roles in tumor progression." (PMID 35615148, 2022). "This could, in part, explain the reduced primary tumor size observed in SLIT2-expressing PDACs38." (PMID 32807784, 2020). "Moreover, the serum levels of Slit2 gradually increased with tumor development in ApcMin/+ mice." (PMID 31242633, 2019). "In addition, Slit2 expression in the tumor tissues of patients with CRC was gradually upregulated with the increase of the CRC pathological stage, and was markedly higher than that in normal human intestine tissues when the clinical pathological stage reached stage 2." (PMID 31242633, 2019). "Additionally, Slit2 was gradually increased during tumor development." (PMID 31242633, 2019). "In addition, TECs downregulate tumor-suppressive factors such as Slit2." (PMID 31600937, 2019). "We hypothesized that Slit2/Robo1 signaling might be involved in the tumor development of CRC." (PMID 31242633, 2019). "Thus, Slit2/Robo1 signaling plays a tumor-promoting role during the intestinal tumorigenesis." (PMID 25605242, 2015). "Therefore, if Slit2 were promoting tumor cell migration, Src may also be expected to increase Robo1 expression in transformed cells." (PMID 21301049, 2010). "In summary, our experimental results suggest that significant upregulation of the Robo1 gene in response to removal of miR-218 may induce a subsequent upregulation of the Slit-Robo1 pathway through its interaction with Slit2, facilitating tumor cell migration and invasion." (PMID 20300657, 2010). "All RCC with SLIT2 methylation also contained unmethylated SLIT2 alleles, which might be attributable to the presence of contaminating normal tissue (tumour samples were not microdissected)." (PMID 14735202, 2004). "Furthermore, in in vitro assays, SLIT2 suppressed tumour growth." (PMID 15534609, 2004). "Using the slit guidance ligand 2 (SLIT2)‐trapping protein Robo1Fc effectively inhibits macrophage infiltration and tumor growth in GBM mouse models, significantly improving the antitumor effects by its combination with anti‐PD‐1 and anti‐4‐1BB therapies." (PMID 40843131, 2025). "SLIT2 has been shown to inhibit EMT, suppress angiogenesis, and negatively regulate cell migration and invasion, suggesting a protective role against tumor progression." (PMID 40362385, 2025). "Nevertheless, NCAM1, NRCAM, SLIT2, ALCAM, NRP1, and NRP2 also showed mild expression in Stage 4 tumor cells (primarily in cluster cIV)." (PMID 40448172, 2025).
tumor (continued). "Follow-up research confirmed an increased promoter methylation in key tumor suppressor genes such as MYC and SLIT2, likely leading to reduced gene expression and contributing to tumor growth." (PMID 40299416, 2025). "As we can see in our results, SLIT1 and SLIT2 are more expressed in the PTEN model, which presents a more advanced tumor characterized by stromal invasion." (PMID 40508075, 2025). "We also demonstrate that, by acting as a miRNA sponge, PGM5-AS1 binds to miR-423-5p to regulate expression of its target gene slit guidance ligand 2 (SLIT2), a tumor-suppressor in NSCLC and other types of cancer." (PMID 38902704, 2024). "SLIT2 has been identified as a tumor suppressor gene in SCLC, with its expression significantly reduced in this type of tumor, while ROBO1 expression is significantly higher in SCLC cells compared to adjacent normal cells." (PMID 38983267, 2024). "Analysis of human samples showed reduced levels of Slit2 and increased levels of Robo1 in SCLC tumors, confirming the tumor‐suppressive function of Slit2 and the oncogenic role of Robo1 observed in our in vitro and in vivo studies." (PMID 35838343, 2023). "We also find that hepatocyte-derived SLIT2 forms a supportive environment for the implantation of ROBO1-positive DTCs, thus triggering coadaptation of hepatocytes and tumour cells to further support the development of the MMN." (PMID 36792623, 2023). "SLIT2 suppresses, whereas ROBO1 promotes, SCLC growth by regulating the Tgf‐β1/glycogen synthase kinase‐3 beta (GSK3)/β‐catenin signaling pathway in tumor cells and TAMs." (PMID 35838343, 2023). "By profiling the immune cells in Slit2‐ and control‐treated SCLC tumors, we found higher numbers of anti‐tumor M1‐like macrophages." (PMID 35838343, 2023). "The SLIT2-rich liver microenvironment not only supported the survival and outgrowth of disseminated ROBO1+ tumour cells but also exerted selective pressure on DTCs to enrich ROBO1+ cells." (PMID 36792623, 2023). "And both down-regulation of SLIT2 expression and over-expression of ROBO1 can promote tumor growth and metastasis." (PMID 37059586, 2023). "On the contrary, several studies have shown that the SLIT2/ROBO1 signal suppresses neovascular formation, especially in tumor angiogenesis." (PMID 35615148, 2022). "To identify differentially methylated CpGs at the promoter regions of SLIT genes, we analyzed methylation statuses of SLIT1, SLIT2 and SLIT3 genes in tumor and matched normal tissues from 42 NSCLC patients previously reported." (PMID 35053460, 2022). "mRNA levels of SLIT2, ROBO2, ROBO3, ROBO4 were significantly downregulated in tumor tissues compared to normal tissues." (PMID 35053460, 2022). "At first, when a fibroblast is in the early stages of activation, SLIT2 increases and inhibits the expression of CXCL12, leading to the prevention of tumour growth and metastasis." (PMID 36555218, 2022). "In order to assess the possible role of each drug on brain metastasis, eight protein/gene effectors known to have a more important role in brain metastasis than in primary tumours were considered: FGFR1; Ki-67, ROBO1; S100A7; S100B; SIRT1; SLIT2; and VEGFA." (PMID 33659043, 2021). "By transplanting myeloablated PyMT with Slit2- or PBS-treated allografts, we observed that Slit2 brought about changes directly in BMDM of tumor-bearing mice, which in turn enhanced their antitumor macrophage population and reduced tumor progression." (PMID 34777365, 2021). "By contrast, SLIT2, EFNB2, FGF9, and HEY1, which promote tumor angiogenesis, were downregulated in 9F-treated HCT116 cells." (PMID 32106543, 2020). "Inprostate cancer, the tumor-promoting effect of EZH2 is attributed to itsinhibitory action on the transcription of multiple genes, includingDAB2IP, ADRB2, SLIT2, andE-cadherin (Yu etal., 2007; Minet al., 2010; Yuet al., 2010)." (PMID 32453339, 2020).
tumor (continued). "According to the model outputs, when a fibroblast is in normal status, SLIT2 increases and inhibits CXCL12 expression which leads to prevention of tumor growth and metastasis." (PMID 32384110, 2020). "The blocking of Slit2/Robo1 signaling by R5 attenuated TGF-β1 phosphorylation of Smad2 and Smad3 in Lovo cells, SW480 cells, and tumor tissues of ApcMin+ mice compared with mIgG-treated groups." (PMID 31242633, 2019). "MiR-218-5p, a vertebrate-specific intronic miRNA co-regulated with its host genes SLIT2/SLIT3, functions as a tumor suppressor by modulating multiple pathways." (PMID 30699189, 2019). "Our study confirmed that SLIT2 and ROBO1 are upregulated in OS; inhibiting SLIT2/ROBO1 signaling by the silencing of ROBO1 or SLIT2 produced an anti-tumor effect." (PMID 29523788, 2018). "Recently, an increasing number of studies have found that the SLIT2/ROBO1 signalling pathway is closely involved in tumourigenesis by inhibiting the proliferation, migration, and invasion of tumour cells." (PMID 29743814, 2018). "Further disruption of SLIT2 and ROBO1 has been shown to induce SDF1 and CXCR4 shifting the tumor microenvironment in an increased inflammatory state and further promoting invasion." (PMID 28440283, 2017). "To further investigate lung tumorigenesis, we also analyzed the expression of SLIT2 and SLIT3 since miR-218 co-expresses with these host tumor suppressor genes." (PMID 28830450, 2017). "Different from the significant inhibitory effect on tumors for SLIT2, SLIT3 remains controversial in the progression versus suppression due to tumor species specificity." (PMID 27974673, 2017). "Secondly, miR-218 host genes SLIT2 and SLIT3 promoters are hypermethylated in the majority of CRC cell lines and tumor specimens." (PMID 27462788, 2016). "14.7% (5/34) of benign lesions, 36.4% (16/44) of DCIS and 39.8% (47/118) of IDC tissue specimens showed low expression of Slit2 (P = 0.024)." (PMID 26400100, 2015). "By immunofluorescence staining a strong nuclear translocation of β-catenin has been observed in the tumor cells of the ApcMin/+;Slit2 and DMH/DSS-Slit2 mice." (PMID 25605242, 2015). "The miR-218 transcripts are located within the introns of SLIT2 (pri-mir-218-1) and SLIT3 (pri-mir-218-2), which were reported to function as tumor suppressors." (PMID 24705471, 2014). "In the network, Slit2 and Slit3 were redundantly activating Robo1, Robo2, Robo4 and ITGA1 receptors in tumor." (PMID 24597571, 2014). "Frequencies of hypomethylation of LINE-1 and hypermethylation of SLIT2, MAL and IGFBP7, defined by predetermined cut off values, were 55, 64, 46 and 54% in NSCLCs, respectively and exhibited tumor-specific features." (PMID 23381221, 2013). "Multiparous (≥5) women with altered SLIT2 and ROBO1 along with advanced tumor stage (III/IV) and early sexual debut (<19 years) had worst prognosis." (PMID 22719878, 2012). "The frequency of SLIT2 methylation in clear cell RCC (24%, nine out of 37) was similar to that found in all tumour types." (PMID 14735202, 2004). "SLIT2 has been shown to inhibit EMT in CRC through the protein kinase B-glycogen synthase kinase 3 β (AKT-GSK3β) signaling pathway; therefore, the hypermethylation of SLIT2 promoter reverses the inhibition of EMT, facilitating tumor progression." (PMID 40362385, 2025). "Importantly, ROBO1 and SLIT2 jointly promote RGC axon growth and play roles in neuronal axon guidance, angiogenesis, inflammatory cell chemotaxis, and tumor cell migration and transfer." (PMID 39574940, 2024). "Overall, we show that Slit2/Robo1 signaling is tumor suppressive in SCLC, suggesting that Slit2 may represent an ideal substrate for the development of an immune‐based therapeutic agent." (PMID 35838343, 2023). "The results demonstrated that SLIT2 is derived from cancer-associated fibroblasts (CAFs) in patients and KPC mouse models but not from ROBO1+ tumour cells." (PMID 36792623, 2023).
tumor (continued). "Based on these results, we propose that Slit2 directly binds to Robo1 and acts as an important tumor‐suppressor, however, in the absence of Slit2, Robo1 promotes SCLC tumorigenesis in a ligand‐independent manner." (PMID 35838343, 2023). "Moreover, SLIT2 and ROBO1 have also been reported to inhibit tumor metastasis by reducing cell adhesion and increasing cell migration and metastasis." (PMID 37238655, 2023). "Finally, we determined that hepatocyte-derived Slit2, a member of the AG family, was enriched in the PMN and MMN, allowing tumour cells to thrive." (PMID 36792623, 2023). "Interestingly, β‐catenin in SBC5‐Robo1KO and Slit2‐treated xenografts was translocated to the cell membrane, while it was present in the nucleus of SBC5‐Scr tumor cells." (PMID 35838343, 2023). "Similarly, Ad‐Slit2‐treated SBC5‐Scr tumors showed significantly reduced tumor growth and tumor weight compared with control SBC5‐Scr." (PMID 35838343, 2023). "Five CpGs at the CpG island of SLIT1, SLIT2 or SLIT3 genes were significantly (Bonferroni corrected p < 0.05) hypermethylated in tumor tissues obtained from 42 NSCLC patients than in matched normal tissues." (PMID 35053460, 2022). "In addition, at the protein level, FGF18, IL23A, LIF, and VGF stained more deeply in tumor tissues than in normal tissues, while CCL28 and SLIT2 were only deeply stained in normal intestinal mucosal tissues according to the Human Protein Atlas." (PMID 34017356, 2021). "This suggests that Slit2 attenuates tumor growth and progression, such that mice with palpable tumors do not show significant increase in tumor growth when treated with Slit2." (PMID 34777365, 2021). "We show that SLIT2, in a ROBO1-dependent manner, negatively impacts the survival of KRAS-transformed cancer cells by inhibiting macropinocytosis, thus limiting protein uptake in a Glut-deprived state similar to the tumor microenvironment found in vivo." (PMID 32807784, 2020). "The candidate tumor suppressor genes were ZBTB16, MAL, LIFR, and SLIT2." (PMID 33193630, 2020). "The tumor suppressor genes were ZBTB16, MAL, LIFR, and SLIT2." (PMID 33193630, 2020). "In this study, we performed data mining in the Metabolic gEne RApid Visualizer (MERAV) database and found that Slit2 and TGF-β1 (Transforming growth factor-β1) are highly expressed in carcinomas relative to those in tumor-free tissues from healthy volunteers or wild type mice." (PMID 31242633, 2019). "Surprisingly, we clarified that tumor metastasis, but not tumor growth of CRC is dependent on Slit2/Robo1 signaling induced activation of the TGF-β/Smads pathway." (PMID 31242633, 2019). "Among these four genes, we determined that SOX7-activated SPRY1 and SLIT2, and SOX7-repressed TRIB3 and MTHFD2 could all differentially contribute to SOX7-mediated tumor suppression." (PMID 29757932, 2018). "Upon macroscopic examination, it was revealed that ApcMin/+;Slit2 mice and the DMH/DSS-Slit2 mice exhibited a significantly increased tumor incidence (the number of tumors) and tumor burden (average tumor size), compared with ApcMin/+ mice and DMH/DSS-C57 mice." (PMID 25605242, 2015). "Comparisons of tumor tissue with matched non-malignant lung tissue indicated that aberrant methylation of LINE-1, SLIT2, MAL and IGFBP7 were all tumor-specific events (all P<0.0001), despite the fact that tumor tissues consist of mixtures of tumor cells and non-malignant cells." (PMID 23381221, 2013). "Moreover Cox multivariate analysis revealed alterations of SLIT2 and ROBO1, in combination with advanced tumor stage (III/IV), multiparity (≥5) and early sexual debut (<19 years) as determinants of worse prognosis." (PMID 22719878, 2012). "The Cox multivariate analysis indicated that alterations of SLIT2 and ROBO1 along with advanced tumor stage (III/IV), multiparity (≥5) and early sexual debut (<19 years) were determinants of poor prognosis for CACX patients, thereby enabling efficient classification of the high-risk patients." (PMID 22719878, 2012).